TES (testin LIM domain protein)
Description:
Scaffold protein that may play a role in cell adhesion, cell spreading and in the reorganization of the actin cytoskeleton. Plays a role in the regulation of cell proliferation. May act as a tumor suppressor. Inhibits tumor cell growth.
Synonyms: DKFZP586B2022; TESS-2; TESTIN; TESS
Tractability: Antibody: its Gene Ontology location is reachable by antibodies, with high confidence. PROTAC: ubiquitination databases record sites on it; its protein half-life has been measured.
Target class: Structural protein
Gene: Protein-coding gene on chromosome 7 (116,210,493 to 116,258,789, forward strand). Ensembl gene ENSG00000135269.
Subcellular location: Cytoplasm; Cell junction, focal adhesion
Subcellular location (Human Protein Atlas): Cytosol; Focal adhesion sites; Cell Junctions; Plasma membrane
Gene Ontology:
Molecular function: cadherin binding; protein binding; RNA binding; zinc ion binding
Biological process: negative regulation of cell population proliferation
Cellular component: cytosol; focal adhesion; nucleus; protein-containing complex; cytoplasm
Genetic constraint (gnomAD): Loss-of-function variants: 41 observed, 47.52 expected, observed/expected ratio (o/e) 0.86, 90% interval 0.67 to 1.12. The upper end of that interval is the gene's LOEUF score, 1.12, which puts it in group 4 of 6, group 1 being the genes least tolerant of losing a copy. Missense variants: 463 observed, 531.99 expected, observed/expected ratio (o/e) 0.87, 90% interval 0.81 to 0.94. Synonymous variants: 162 observed, 179.03 expected, observed/expected ratio (o/e) 0.9, 90% interval 0.8 to 1.03.
Homologues: Orthologues: macaque TES (99% identical), chimpanzee TES (99% identical), pig TES (97% identical), dog TES (95% identical), rabbit TES (93% identical), rat Tes (93% identical), guinea pig TES (91% identical), mouse Tes (91% identical), tropical clawed frog tes (81% identical), mouse Tesl1 (77% identical), rat Tesl1 (73% identical), rat Tesl (72% identical), and 5 more. Paralogues in human: LMCD1 (43% identical), PRICKLE1 (31% identical), LIMD2 (7% identical).
Diseases named in the same sentence as TES in open-access papers:
TES is named in the same sentence as 37 diseases in open-access papers, as found by Europe PMC text mining. Sharing a sentence is not in itself a finding about the gene and the disease. The quoted sentences say what the papers report.
gastric cancer (8 papers, 2010 to 2024). A primary or metastatic malignant neoplasm involving the stomach. "Like OSR1, TES (testin LIM domain protein) functions as a Mena-dependent tumour suppressor gene in many cancers, including gastric cancer, with loss of expression associated with cancer progression." (PMID 38694815, 2024). "TES serves as a tumor suppressor in several cancers, such as gastric cancer and breast cancer, and overexpression of TES reduces the oncogenicity and metastasis of tumor cells." (PMID 35935823, 2022). "TES is a scaffold protein that contributes to cell adhesion and cell spreading; however, it may act as a tumor suppressor in gastric cancer." (PMID 36589226, 2022). "However, HMT of CpG islands observed in the region of TES gene resulted in downregulation of TES gene and protein level in primary gastric cancer." (PMID 30357755, 2019). "In our previous study, we identified a candidate tumor suppressor gene, testin LIM domain protein (TES), in primary gastric cancer (GC)." (PMID 30728082, 2019).
ovarian carcinoma (6 papers, 2010 to 2022). A malignant neoplasm originating from the surface ovarian epithelium. "The expression of TES is downregulated in a variety of tumor cell lines, particularly hematopoietic, breast, and ovarian cancer cell lines as well as in primary tumors." (PMID 27323777, 2016). "TES methylation has been shown in primary tumours, including glioblastomas (18 of 31) and ovarian cancer." (PMID 20573277, 2010). "In addition, qRT-PCR results revealed the expression of CDK4, FGF5, MEIS1, and TES genes was significantly increased in CFP1-deleted ES-2 ovarian cancer cells." (PMID 35864225, 2022). "TES mutations have been reported in T ALL (CCRF-CEM), breast cancer and ovarian cancer cell lines and we hypothesised that the less methylated ALL samples may contain coding mutations." (PMID 20573277, 2010). "Furthermore, the deregulation of other downregulated genes following RBPMS knockout, including PDGFD, TES, CARD16, and KNF521, has been linked to the progression of many cancer types, and the role of these genes in the ovarian cancer setting should be investigated." (PMID 35008958, 2022). "TES has been identified as a TSG in many types of tumors, such as uterine cancer, ovarian carcinoma, breast cancer, endometrial carcinoma, head and neck squamous cell carcinoma, and non-small cell lung cancer." (PMID 30728082, 2019). "In ovarian cancer, some of the most frequently methylated genes include OPCML (tumor suppressor activity), TES (involved in regulation of cell motility) and RASSF1A (tumor suppressor activity as well as an inhibitor of the anaphase-promoting complex)." (PMID 31608277, 2019). "Lack of TES mRNA expression was found in several cancer-derived cell lines, particularly hematopoietic, breast, prostate, and ovarian cancer cell lines as well as in primary tumors." (PMID 27323777, 2016).
breast carcinoma (5 papers, 2010 to 2022). "A heterozygous mutation at codon 221 in exon 4 of TES has been reported in the breast cancer cell line MDA-MB 453 and in head and neck squamous cell carcinoma tissues." (PMID 20626849, 2010). "Consistent with our findings, a previous study showed that overexpression of TES significantly inhibited breast cancer cell invasion and reduced breast cancer cell metastasis to the lung through blocking the secretion of matrix metallopeptidase-2 (MMP-2)." (PMID 30728082, 2019).
endometrial carcinoma (3 papers, 2016 to 2019). A malignant tumor arising from the epithelium that lines the cavity of the uterine body. "Overexpression of TES also markedly inhibited the invasion and metastasis of endometrial carcinoma and non-small cell lung cancer." (PMID 30728082, 2019).
glioblastoma (3 papers, 2010 to 2014). The most malignant astrocytic tumor (WHO grade IV). "TES methylation is closely associated with loss of TES expression in cell lines and in glioblastoma cells." (PMID 20573277, 2010). "Our findings suggest that the TES gene is a novel tumor suppressor gene and might represent a valuable prognostic marker for glioblastoma, indicating a potential target for future GBM therapy." (PMID 25498217, 2014). "Importantly, both TAGLN and TES have been characterized as tumor suppressors in malignancies outside the brain and the latter is often silenced by promoter hypermethylation in glioblastoma." (PMID 23046790, 2012). "We found that TES was down-regulated in both glioblastoma cell lines and GBM tissues." (PMID 25498217, 2014). "Using whole-genome DNA methylation microarray we found that the TES gene is a novel tumor suppressor gene and might represent a valuable prognostic marker for glioblastoma, indicating a potential future target for GBM therapy." (PMID 25498217, 2014). "Similarly, TAGLN and TES were absent or low in most GNS cell lines, but displayed the opposite trend in glioblastoma tissue compared to normal brain or grade III astrocytoma." (PMID 23046790, 2012).
acute lymphoblastic leukaemia (2 papers, 2010 to 2024). "Testin protein (encoded by TES) is expressed in almost all normal human tissues, while low or lack of Testin expression has been found in prostate cancer, endometrial carcinoma, ovarian, breast, acute lymphoblastic leukemia and nasopharyngeal carcinoma." (PMID 38627776, 2024).
colorectal cancer (2 papers, 2016 to 2019). A primary or metastatic malignant neoplasm that affects the colon or rectum. "TES functions as a necessary tumor suppressor of colorectal cancer progression by activating mitogen-activated protein kinase (p38-MAPK) signaling pathways." (PMID 30728082, 2019). "To investigate its role in colorectal cancer (CRC), we examined TES protein levels in CRC tissue samples and cell lines." (PMID 27323777, 2016).
leukaemia (2 papers, 2010 to 2016). "TES promoter methylation resulted in a reduction of TES expression in the leukaemia cell lines tested in agreement with previously published reports." (PMID 20573277, 2010). "The relationship between TES expression and methylation was examined directly in available leukaemia cell lines." (PMID 20573277, 2010).
pancreatic cancer (2 papers, 2022). "Furthermore, we also found that the expression of TES and LDHA was significantly associated with survival of pancreatic cancer patients." (PMID 35789607, 2022). "Furthermore, the qPCR results indicated the mRNA expression levels of JMJD6, ANKZF1, CITED2, and ENO3 was obviously decreased in pancreatic cancer cells versus the normal pancreatic ductal epithelial cells, whereas those of LDHA, TES, and SIAH2 were oppisite." (PMID 35935823, 2022). "Unlike TES, LDHA together with KLF4 or c-Myc has been found to positively regulate aerobic glycolysis and promote tumor progression in pancreatic cancer." (PMID 35789607, 2022).
prostate carcinoma (2 papers, 2016 to 2024). A carcinoma that arises from epithelial cells of the prostate gland. "The human TESTIN gene, also known as TES, has been implicated in cancer due to its loss of expression in prostate cancer, its presence at the sites of focal adhesions, and its role in cytoskeletal organization." (PMID 27323777, 2016).
prostate tumors (2 papers, 2014 to 2019). "In comparison, LOH of at least one locus on 7q31 was detected in 34% of sporadic prostate tumours, and the candidate tumour suppressor gene TES was found here." (PMID 24581183, 2014). "Quantified analysis by RT-PCR displayed that only TES gene showed decrease expression in all types of prostate tumors, supporting tumor suppressor gene hypothesis." (PMID 30357755, 2019).
uterine cancer (2 papers, 2016 to 2019). Primary or metastatic malignant neoplasm involving the uterine corpus and/or the cervix. "It has been demonstrated that overexpression of TES suppresses tumor cell growth and induces apoptosis in breast and uterine cancer." (PMID 27323777, 2016). "TES has been identified as a putative TSG in many human cancers, such as breast and uterine cancers and glioblastoma." (PMID 30728082, 2019).
amebiasis (1 paper, 2015). A parasitic infectious disorder caused by amoebas. "The Tc-TES-26 Luminex assay showed more cross-reactivity than the Tc-CTL-1 Luminex; only amebiasis and E. nana infections cross-react with Tc-CTL-1." (PMID 26485145, 2015).
B cell lymphoma (1 paper, 2016). "As we were focussed on TES re-expression in B cells, we proceeded with transfections of NALM6 (B ALL; TES-negative) and Raji (mature B cell lymphoma; TES-positive) cell lines." (PMID 26985820, 2016).
cardiac hypertrophy (1 paper, 2019). "Our study is the first to prove that TES is a reverse modulator of cardiac hypertrophy in cardiomyocytes, and it did so with an adeno‐associated virus expression system." (PMID 30467953, 2019). "Our research is the first of its kind to prove the participation of TES in cardiac hypertrophy and to suggest that proteins consisting of LIM domains can act as a reservoir of signalling agents related to the preservation of cardiac homeostasis." (PMID 30467953, 2019). "Our study is the first to prove that TES upregulation inhibits the calcineurin‐NFAT axis in cardiac hypertrophy." (PMID 30467953, 2019). "The findings of our study revealed that TES expression was remarkably suppressed not only in failing human hearts but also in mouse hearts with cardiac hypertrophy." (PMID 30467953, 2019). "In all, our study revealed a novel role for TES in the modulation of pathological cardiac hypertrophy through suppression of the calcineurin‐NFAT axis." (PMID 30467953, 2019). "Our study proved that TES expression was inhibited in failing human heart specimens as well as in murine cardiac hypertrophy models triggered by pressure overload." (PMID 30467953, 2019).
cervical intraepithelial neoplasia (1 paper, 2024). "However, TES overexpression has been noted in progressive cervical intraepithelial neoplasia." (PMID 38694815, 2024).
colon cancer (1 paper, 2016). "To confirm TES tumor suppressor function in CRC, we chose HCT116 and DLD-1 cells for their moderate TES protein levels, and then established colon cancer cell lines that stably overexpress TES or shRNA-targeting TES." (PMID 27323777, 2016). "Western blot analysis and real-time qPCR demonstrated that CRC specimens and all of the nine kinds of colon cancer cells exhibited significantly reduced TES protein and mRNA compared with the adjacent tumor-free tissue samples and the two kinds of normal colon cells." (PMID 27323777, 2016). "Additionally, overexpression of TES significantly inhibited cell proliferation, migration, and invasion, while increasing cell apoptosis in colon cancer cells." (PMID 27323777, 2016). "Increased TES expression reduced the migration and invasion ability of colon cancer cells in vitro." (PMID 27323777, 2016). "To investigate whether TES has a similar effect in CRC cells, we evaluated the migration and invasion ability of TES-overexpressing and knockdown HCT116 and DLD-1 colon cancer cells." (PMID 27323777, 2016).
immune deficiency (1 paper, 2025). "Through differential analysis, three key genes – GNAQ, ELP3, and TES – were identified as closely linked to processes related to ribosome biogenesis, DNA replication, and congenital immune deficiency." (PMID 39925840, 2025).
lymphoma (1 paper, 2010). A malignant (clonal) proliferation of B- lymphocytes or T- lymphocytes which involves the lymph nodes, bone marrow and/or extranodal sites. "However, TES expression failed to be correlated with age, sex, tumor size, metastasis, lymphoma invasion, T stage and clinical stage (p > 0.05)." (PMID 20626849, 2010).
mesothelioma (1 paper, 2024). A usually malignant and aggressive neoplasm of the mesothelium which is often associated with exposure to asbestos. "We note that the increased expression of NDUFA1, TES and IL13RA1 associated with poor survival outcome in the TCGA mesothelioma cohort contrasted with the literature." (PMID 38694815, 2024).
myelodysplastic syndrome (1 paper, 2016). A clonal hematopoietic disorder characterized by dysplasia and ineffective hematopoiesis in one or more of the hematopoietic cell lines. "TES is located on the long arm of chromosome 7, in a region frequently displaying loss of heterozygosity in many tumours, including myelodysplastic syndrome and myeloid leukaemias." (PMID 26985820, 2016).
myeloid malignancies (1 paper, 2010). "TES is located in 7q31.2, a region showing frequent loss of heterozygosity in myeloid malignancies (between D7S2554 and D7S2460)." (PMID 20573277, 2010).
osteosarcoma (1 paper, 2021). A usually aggressive malignant bone-forming mesenchymal neoplasm, predominantly affecting adolescents and young adults. "Our results confirmed that SCD3, EGFR, and MXI1 were remarkably up-regulated while CAVIN1 and TES were prominently down-regulated in U2OS osteosarcoma cells compared with hFOB1.19 normal cells." (PMID 35071320, 2021). "Additionally, our experimental results confirmed that SCD3, EGFR, and MXI1 were remarkably up-regulated while CAVIN1 and TES were prominently down-regulated in osteosarcoma cells compared with normal cells." (PMID 35071320, 2021). "In the five-gene signature, we separately evaluated the prognostic potential of CAVIN1, EGFR, SCD3, TES, and MXI1 in osteosarcoma." (PMID 35071320, 2021).
renal carcinoma (1 paper, 2022). A carcinoma arising from the epithelium of the renal parenchyma or the renal pelvis. "In contrast, high expression of FRZB, MYBL2, MYL2, NETO2, PLSCR4, and TES predicts an unfavorable outcome in endometrial, head and neck, liver, pancreatic, and renal cancer." (PMID 36497479, 2022).
tumor (25 papers, 2009 to 2024). "In the patients with high Mena expression, TES expression was negatively associated with tumor infiltration, lymph node metastasis, TNM stage, and prognosis." (PMID 30728082, 2019). "In GC patients with high Mena expression, the expression of TES was associated with tumor infiltration (P = 0.005), lymph node metastasis (P = 0.003), TNM stage (P = 0.003), and prognosis (P = 0.010)." (PMID 30728082, 2019). "TES is a putative tumour suppressor gene located on chromosome 7q31 that encodes the highly conserved TESTIN protein." (PMID 26985820, 2016). "Deletion or reduced TES protein expression was associated with tumor differentiation; the lower the differentiation, the lower TES expression." (PMID 20626849, 2010). "Interestingly, in the group with high Mena expression, TES expression was negatively associated with tumor infiltration (P = 0.005), local lymph node metastasis (P = 0.003), and TNM stage (P = 0.003)." (PMID 30728082, 2019). "With respect to TES, while it has been reported to act as a tumor suppressor in other tumor types, in pancreatic cancer its increased expression seems to be associated with worse survival." (PMID 36831579, 2023). "Among the three hypoxia-related genes, the TES gene appeared to possess the properties of a tumor suppressor." (PMID 35789607, 2022). "In this study, we systematically explored the tumor suppressive functions of TES in GC both in vitro and in vivo and determined its interaction with Mena in GC." (PMID 30728082, 2019). "Ad-TES transfection remarkably delayed the tumor formation of SGC7901 and MKN45 cells in nude mice as compared with Ad-Control transfection." (PMID 30728082, 2019). "Overexpression of TES significantly inhibited tumor cell growth in vitro and reduced the tumorigenic potential of certain tumor cell lines in vivo." (PMID 30728082, 2019). "TES as a putative tumour suppressor gene is likely to be transcriptionally active in normal tissues." (PMID 26985820, 2016). "We observed that TES overexpression remarkably inhibited tumor formation and growth in vivo, whereas TES knockdown significantly facilitated tumor formation and growth in vivo, evaluated by the volume and weight of xenograft tumors." (PMID 27323777, 2016). "The human TESTIN (TES) gene has been identified as a candidate tumor suppressor based on its location at a common fragile site – a region where loss of heterozygosity has been detected in numerous types of tumors." (PMID 27323777, 2016). "Testin (TES) is a zyxin-related LIM-domain protein with tumor suppressive activity that interacts with zyxin and VASP family proteins at integrin-based FAs25." (PMID 26611125, 2015). "Herein, we examined the expression of TES in human GBMs and investigated the biological role of TES in the pathogenesis of this tumor." (PMID 25498217, 2014). "Among GBM samples, reduced TES protein level was detected in 33 (89.2%) of 37 tumor tissues by immunohistochemical staining." (PMID 25498217, 2014). "Down regulation of TES was shown to be correlated with tumor differentiation (p = 0.035) and prognosis (p = 0.035, log-rank test)." (PMID 20626849, 2010). "The function of TES is poorly understood, but it has been proposed to act as a tumor suppressor." (PMID 37902809, 2023). "The tumour suppressor gene, TES, is frequently methylated in many human tumours." (PMID 33004921, 2020). "Furthermore, we found that the TES promoter was frequently hypermethylated in primary GC tissues and GC cell lines, and the protein expression of TES was significantly decreased in 72% GC tissues as compared with matched non-tumor tissues." (PMID 30728082, 2019). "We believe that TES functions as a Mena-dependent tumor suppressor." (PMID 30728082, 2019). "Taken together, these data implicate TES as a putative tumor suppressor gene." (PMID 27323777, 2016).